EIF4G2 (eukaryotic translation initiation factor 4 gamma 2)
Diseases named in the same sentence as EIF4G2 in open-access papers (continued):
Sharing a sentence is not in itself a finding about the gene and the disease.
tumor (19 papers, 2008 to 2025). "For example, modified by m6A and recognised by YTHDF3, some circRNAs were reported to encode short peptides under the regulation of eukaryotic translation initiation factor 4 gamma 2 (eIF4G2), promoting tumour progression." (PMID 38073586, 2023). "Next, through the database analysis, we observed that EIF4G2 expression was involved in tumor immune infiltration, and was positively associated with CD8+ T cell, neutrophil, macrophage, and dendritic cell infiltration levels." (PMID 36157241, 2022). "Additionally, several somatic mutations in the EIF4G2 gene have been identified in primary tumours from cancer patients." (PMID 40276932, 2025). "Thus, EIF4G2 was associated with the development and treatment of tumor." (PMID 35196197, 2022). "Therefore, EIF4G2 has been found to be associated with tumor development and treatments." (PMID 33526055, 2021). "This infers a survival advantage to tumor cells that display lower expression levels of EIF4G2 expression, with implications for enhanced drug resistance and/or recurrence." (PMID 38388710, 2024). "On the contrary, EIF4G2 expression was observed to be reduced in bladder cancer, correlating with tumor dedifferentiation and invasiveness." (PMID 38129098, 2024). "Paradoxically, a limited number of studies have attributed both oncogenic and tumor-suppressive capabilities to EIF4G2." (PMID 38388710, 2024). "On the other hand, EIF4G2 expression was reduced in bladder cancer, correlating with tumor de-differentiation and invasiveness." (PMID 38388710, 2024). "The Tumor-Immune System Interaction database was employed to analyze the correlation between EIF4G2 expression and tumor-infiltrating lymphocytes." (PMID 36157241, 2022). "The Tumor Immune Estimation Resource 2.0 database was used to analyze EIF4G2 expression in various cancers and the relationship between EIF4G2 expression and tumor-infiltrating immune cells." (PMID 36157241, 2022). "The LC cell lines with stable intervention of circ-UBE2D2, miR-376a-3p, and EIF4G2 expression are constructing to investigate the effects of circ-UBE2D2/miR-376a-3p/EIF4G2 axis on tumor growth in vivo." (PMID 35196197, 2022). "Multiple studies have elucidated that EIF4G2-dependent mRNAs are specifically emerging in cancer-facilitating activities like cell proliferation, anti-apoptosis, tumor invasion, metastasis and angiogenesis." (PMID 35196197, 2022). "Many studies have suggested that EIF4G2-dependent mRNAs were specifically involved in pro-oncogenic activities, such as cell proliferation, anti-apoptosis, tumor invasion, metastasis and angiogenesis." (PMID 33526055, 2021). "The curves revealed that there was a significant tumor growth inhibition in the EIF4G2 silencing group." (PMID 33526055, 2021). "Upregulation of the lnRNA succinate dehydrogenase complex flavoprotein subunit A pseudogene 1 (lncRNA SDHAP1) in tumor ovarian cells contributes to PTX resistance through miR-4465-eukaryotic translation initiation factor 4 gamma 2 (EIF4G2)." (PMID 33348838, 2020). "By fusing a gasdermin D mutant to a mitochondrial-targeting peptide, they harnessed mitochondrial inner membrane cardiolipin toxicity to trigger mitophagy-mediated tumor cell death, which markedly suppressed tumor growth in xenograft models of EIF4G2+/PTBP1+ adenocarcinomas." (PMID 41226581, 2025). "The results showed that EIF4G2 could be involved in the regulation of tumor immune infiltration in GC." (PMID 36157241, 2022). "Moreover, the increasing expression of EIF4G2 in higher tumor stages and grades also indicated shorter OS." (PMID 36157241, 2022). "Immune infiltration analysis indicated that EIF4G2 expression may be involved in the modulation of tumor immune infiltration in GC." (PMID 36157241, 2022).
tumor (continued). "Obviously, downregulation of EIF4G2 suppressed tumor growth in vivo." (PMID 33526055, 2021). "The function of EIF4G2 in HCC tumor growth was assessed in a xenograft nude mouse model in vivo." (PMID 33526055, 2021). "Consistently, the staining results also showed higher expression of EIF4G2 in HCC tumor tissues." (PMID 33526055, 2021). "These specific functions suggest that EIF4G2 may be critical for cell fate decisions in cancer, although its multiple and sometimes opposing functions make it difficult to predict whether EIF4G2 can promote or suppress tumor development and growth." (PMID 38129098, 2024). "Moreover, the study suggested that EIF4G2 expression may play a role in regulating tumor immune cell infiltration." (PMID 38603733, 2024). "Moreover, our findings showed that EIF4G2 expression may be involved in the modulation of tumor immune cell infiltration." (PMID 36157241, 2022). "Moreover, EIF4G2 participated in the regulation of tumor immune cell infiltration in GC." (PMID 36157241, 2022). "We also found that EIF4G2 could be negatively regulated by the tumor suppressor miR-144." (PMID 33526055, 2021). "The findings revealed significantly elevated protein expression levels of EIF4G2 and SERBP1 in tumor tissues compared to normal ovarian tissues." (PMID 38603733, 2024). "Thus, the limited data to date suggest that EIF4G2 may act as either an oncogene or a tumor suppressor, depending on the tumor context, and call for a broader and deeper investigation into whether EIF4G2 gain or loss of function is indeed associated with cancer development and/or progression." (PMID 38129098, 2024). "Immunohistochemical analysis revealed significantly higher expression levels of EIF4G2, SEPBP1, and DDX3Y in tumor tissues." (PMID 38603733, 2024). "Another discovery confirmed that EIF4G2 is upregulated in HCC tissues, and high expression of EIF4G2 has been strongly correlated with worse prognosis in tumor patients." (PMID 36157241, 2022). "Moreover, EIF4G2 expression may be involved in the regulation of tumor immune cell infiltration." (PMID 36157241, 2022). "Finally, we found that miR-144, as a tumor suppressor, could negatively regulate EIF4G2 expression." (PMID 33526055, 2021). "The eukaryotic translation initiation factors, namely, EIF1, EIF3E, EIF3H, EIF4G2, EIF5, and EIF6, were all upregulated in the brain metastasis-derived tumor cells." (PMID 33170151, 2020). "Death-associated protein 5 (DAP5/eIF4G2), a non-classical translational scaffold, has been reported to support human Treg differentiation in vitro, but its functions in thymic Treg development, peripheral Treg homeostasis, and tumor-infiltrating Treg (ti-Treg) fitness remain unclear." (PMID 41457459, 2025). "Our recent analysis of the TCGA database demonstrated a significant reduction in EIF4G2 mRNA expression in 7/24 primary tumor types compared to healthy tissue, as opposed to 2 tumor types that showed significant increased mRNA expression." (PMID 38388710, 2024). "However, differences in EIF4G2 expression became statistically meaningful when patients were stratified by tumor grade; there was significantly lower OS and RFS in patients with Grade 2 tumors that expressed low levels of EIF4G2." (PMID 38388710, 2024). "Firstly, Tumor Immune Estimation Resource 2.0 (TIMER2.0), Gene Expression Profiling Interactive Analysis (GEPIA), UALCAN databases, and the Kaplan–Meier plotter were employed to analyze the expression level and prognosis of EIF4G2 in GC." (PMID 36157241, 2022). "After PPI hub genes and module analysis as well as miRNA target gene prediction, our present study preliminarily suggests downregulated ATP5H, SOD1 and upregulated EIF4G2, PABPC1 may be especially important genes involved in amorphous SiNPs-mediated tumor initiation." (PMID 30863671, 2019).
tumor (continued). "In triple negative metastatic breast cancer, EIF4G2 was shown to mediate non-canonical translation of targets involved in cell migration, the epithelial-mesenchymal transition (EMT) and invasion, and its overexpression correlated with and promoted tumor metastasis." (PMID 38388710, 2024).
cancer (17 papers, 2019 to 2025). A tumor composed of atypical neoplastic, often pleomorphic cells that invade other tissues. "This is consistent with EIF4G2’s previously reported divergent association with different types and stages of cancers." (PMID 38388710, 2024). "Here, we explored the contribution of EIF4G2 to cancer by screening the COSMIC database for EIF4G2 somatic mutations in cancer patients." (PMID 38129098, 2024). "This work identifies missense mutations in the translation initiation factor EIF4G2 gene in cancer, showing loss-of-function effects on binding to interacting proteins and translational activity." (PMID 38129098, 2024). "To establish a causative connection between low EIF4G2 expression and cancer progression, we stably knocked-down EIF4G2 in two human EC cell lines in parallel." (PMID 38388710, 2024). "Moreover, we identified deleterious mutations and significantly occurring somatic missense mutations in EIF4G2 in various cancers, several of which were proven to be loss-of-function." (PMID 38388710, 2024). "Here, we screened the COSMIC database for EIF4G2 somatic mutations in cancer patients." (PMID 38129098, 2024). "Under conditions of cell stress in cancer cells for example, eIF4G2 is able to drive the cap-independent translation of particular mRNA subsets." (PMID 39971159, 2025). "EIF4G2 is an appealing candidate to be studied in the context of cancer because of its established physiological roles." (PMID 38129098, 2024). "In total, 31 genes were overlapped in both datasets and 12 genes (i.e., CNBP, HDAC2, LDAH, RPL6 and EIF4G2) were annotated in Cancer Gene Census or CancerMine38,39." (PMID 36681772, 2023). "Many studies have reported that EIF4G2 is abnormally expressed in different cancers and has great influence on the progression of tumors." (PMID 36157241, 2022). "EIF4G2 is a kind of eukaryotic translation initiation factor that indirectly participates in the regulation of autophagy in cancer." (PMID 35874628, 2022). "Considering the role of miRNAs in cancer development by restraining targeted mRNAs, we used online database websites to predict the possible miRNAs regulating EIF4G2 expression post-transcriptionally." (PMID 33526055, 2021). "Previous studies have indicated that abnormal expression of EIF4G2 plays key roles on the progression of many cancers." (PMID 33526055, 2021). "The Western blot results showed that the level of EIF4G2 was remarkably upregulated in HCC tissues compared with corresponding para-carcinoma tissues (n = 30)." (PMID 33526055, 2021). "To date, only a small number of studies have examined a direct role of EIF4G2 in cancer." (PMID 38129098, 2024). "In order to further characterize the effect of EIF4G2 protein depletion on cancer outcome, and to understand why EIF4G2KD cells are more resistant to therapies, we examined the prevalence of aggressive sub-populations within the control and EIF4G2KD cells by probing for CD133 (PROM1) and CD44." (PMID 38388710, 2024). "These indicate an important role for EIF4G2 in the translation of factors critical for cell fate decisions in somatic and embryonic stem cells, and it is not surprising that it has been linked to cancer." (PMID 38388710, 2024). "Thus, it appears that EIF4G2’s contribution to cancer varies according to the type and/or stage." (PMID 38388710, 2024). "Furthermore, EIF4G2 KD resulted in enrichment in cells expressing higher levels of markers such as CD133, CD44 and ALDH1A1 associated with aggressiveness, often referred to as cancer stem cells (CSC)." (PMID 38388710, 2024). "Furthermore, aberrant EIF4G2 exerts a critical part in the progression of numerous cancers." (PMID 35196197, 2022). "In certain types of cancers, the eIF3d and eIF4G2 driven mechanism is also used to bypass the global sequestration of eIF4E, thereby allowing EMT, which is a crucial indicator for cancer progression to occur." (PMID 39971159, 2025).
cancer (continued). "Based on the high expression of eIF4G2 and PTBP1 in cancer tissues, Feng and colleagues developed a circular RNA therapeutic that contains Human rhinovirus type 2 (HRV2) IRES to achieve selective translation in cancer cells overexpressing these factors." (PMID 41226581, 2025). "EIF4G2 and PABPC1 may be involved in the progression of cancer by affecting translational initiation, while SOD1 and ATP5H may participate in carcinogenesis via influencing oxidative stress and oxidative phosphorylation." (PMID 30863671, 2019). "EIF4G2 is a non-canonical translation initiation factor that mediates internal ribosome entry site (IRES)- and uORF-dependent initiation mechanisms, which can be used to modulate protein expression in cancer." (PMID 38129098, 2024).
EIF4G2 also shares sentences with these, for which no sentence is quoted: cervical cancer (2 papers); lung cancer (2); acute myeloid leukemia (1); cholangiocarcinoma (1); esophageal carcinoma (1); head and neck squamous cell carcinoma (1); lung squamous cell carcinoma (1); muscular dystrophy (1); nasopharyngeal carcinoma (1); rheumatic diseases (1); schizophrenia (1); stomach adenocarcinoma (1); triple-negative breast carcinoma (1).